GPR50 (G protein-coupled receptor 50)
Description:
G protein-coupled receptor that plays a role in numerous physiological processes including regulation of energy metabolism, neurite outgrowth or cell migration. Promotes self-renewal and neuronal differentiation of neural progenitor cells through activation of the NOTCH and WNT/beta-catenin signaling pathways (By similarity). Modulates the KAT5-dependent glucocorticoid receptor signaling by modulating KAT5 subcellular compartmentalization. Also plays a role in the activation TGFBR1 in the absence of TGFBR2 by interfering with FKBP1A binding to TGFBR1, leading to induction of both canonical and non-canonical SMAD signaling pathways resulting in inhibition of proliferation or promotion of migration. [C-terminal domain]: Upon cleavage by CAPN1, functions as a scaffold in the nucleus for interacting partners such as GTF2I to promote FOS promoter activation.
Synonyms: H9; Mel1c
Tractability: Small molecule: it belongs to a druggable protein family. Antibody: UniProt places it where antibodies can reach, with high confidence; its Gene Ontology location is reachable by antibodies, with high confidence; UniProt predicts a signal peptide or a membrane-spanning region; the Human Protein Atlas places it where antibodies can reach.
Target class: Family A G protein-coupled receptor; Membrane receptor
Gene: Protein-coding gene on chromosome X (151,176,584 to 151,181,465, forward strand). Ensembl gene ENSG00000102195.
Subcellular location: Cell membrane; Postsynaptic density; Nucleus (C-terminal domain)
Subcellular location (Human Protein Atlas): Plasma membrane; Nucleoplasm; Primary cilium; Primary cilium tip
Gene Ontology:
Molecular function: protein binding; G protein-coupled receptor activity; melatonin receptor activity
Biological process: cell-cell signaling; G protein-coupled receptor signaling pathway
Cellular component: nucleus; plasma membrane; postsynaptic density; membrane
Homologues: Orthologues: chimpanzee GPR50 (98% identical), macaque GPR50 (96% identical), dog GPR50 (84% identical), pig GPR50 (80% identical), rabbit GPR50 (72% identical), mouse Gpr50 (71% identical), rat Gpr50 (70% identical), zebrafish mtnr1c (27% identical), tropical clawed frog GPR50 (27% identical). Paralogues in human: MTNR1A (27% identical), MTNR1B (25% identical), NPY2R (13% identical), MCHR1 (12% identical), TACR3 (12% identical), NPY1R (12% identical), NPY4R (12% identical), NPY4R2 (12% identical), GPR83 (12% identical), PROKR2 (11% identical), PRLHR (11% identical), TACR1 (11% identical), and 21 more.
Diseases named in the same sentence as GPR50 in open-access papers:
GPR50 is named in the same sentence as 34 diseases in open-access papers, as found by Europe PMC text mining. Sharing a sentence is not in itself a finding about the gene and the disease. The quoted sentences say what the papers report.
depression (8 papers, 2015 to 2024). "Another GPR50 polymorphism rs561077 was also associated with an increased risk of incident depression specifically." (PMID 27992373, 2017). "It is also possible that GPR50's association with depression occurs via its ability to modulate melatonin signaling, as melatonin reportedly plays a role in depression." (PMID 25798330, 2015). "This study aims to investigate the role of GPR50 gene variants in late-life depression, taking into account antidepressant use and comorbid anxiety, which is frequent in the elderly, while controlling for lipid levels." (PMID 25798330, 2015). "GPR50 is the mammalian orthologue of the melatonin1c membrane-bound receptor which has been identified as a genetic risk factor for bipolar disorder and major depression in women." (PMID 26500489, 2015). "Our results thus provide only weak support for the involvement of GPR50 variants in late-life depression, which appear specific to certain subgroups of depressed individuals (i.e., women and those with more severe forms of depression)." (PMID 25798330, 2015). "The association between GPR50 polymorphisms and the 12-year incidence of depression in women was then examined, while excluding the 195 women with prevalent depression at baseline." (PMID 25798330, 2015). "In chi-squared analysis, associations between GPR50 SNPs and depression or antidepressant use were identified in women only." (PMID 25798330, 2015). "A Scottish case–control study of hospital patients reported female-specific associations between GPR50 variants and three psychiatric conditions (bipolar disorder, major depressive disorder [MDD], schizophrenia)." (PMID 25798330, 2015). "Research on GRP50 polymorphisms is scarce yielding mixed findings for connection between polymorphisms and mood disorder, although one included study in this review found a increase of risk by GPR50 polymorphism rs561077 for incident depression which makes further research necessary." (PMID 33983995, 2021). "Given that confounders could help account for the observed associations, analyses were then adjusted for covariates found to be significantly associated with depression in this population, and which could themselves be associated with GPR50 polymorphisms." (PMID 25798330, 2015). "Our prospective study in the general population has helped clarify the role of GPR50 in mood disorders, by investigating the association between three commonly studied nonsynonymous variants and depression, comorbid depression and anxiety, as well as antidepressant use in the elderly." (PMID 25798330, 2015). "Logistic regression and survival models were used to determine whether three common GPR50 polymorphisms were associated with depression prevalence or the incidence of depression over 12-years." (PMID 25798330, 2015). "The question remains of how could GPR50 influence an individual's risk of depression and why do the associations appear specific to women." (PMID 25798330, 2015). "A recent large cohort study of GPR50 polymorphisms in 1010 elderly men and women showed that women with heterozygous for rs13440581 showed an increased risk of depression and the risk increased when depression was combined with anxiety in women homozygous for rs2072621." (PMID 27992373, 2017). "Importantly, as GPR50 variants appear to influence circulating lipid levels and disrupted lipid metabolism is often seen in patients with affective disorders and more specifically depression, analysis controlling for such measures is thus clearly needed." (PMID 25798330, 2015). "Our results provide evidence of a weak female-specific association between GPR50 variants and late-life depression, which could be specific for more severe depression (i.e., depression comorbid with anxiety, as well as depression despite antidepressant treatment)." (PMID 25798330, 2015).
depression (continued). "While one could argue that confounding is less problematic in genetic association studies, it remains that if GPR50 variants influence health-related outcomes, this could explain their association with depression (depression itself being associated with worse health)." (PMID 25798330, 2015). "Both Δ502-505 and T532A, two GPR50 variations genetically associated with ASD, depression, and bipolar disorders, attenuate the binding of GPR50 to LC3 and the mitochondrial recruitment of GPR50, impairing GPR50-mediated mitophagy and neuronal development." (PMID 39143050, 2024). "Another gene whose expression has been modulated after PS juice consumption was GPR50, a gene involved in late-life depression in certain subgroups of depressed individuals; its down-regulation is associated with torpor enhancement." (PMID 32316129, 2020). "Our prospective study in the general elderly population has attempted to replicate earlier findings of a predominantly female-specific role for GPR50 in depression, while controlling for potential confounding or mediating factors." (PMID 25798330, 2015). "All the prior studies of GPR50 and depression are based on univariate analysis." (PMID 25798330, 2015). "Two GPR50 variations, Δ502-505 and T532A, have been detected in patients with ASD, bipolar disorder, and major depression." (PMID 39143050, 2024). "Considering the genetic link of GPR50 to ASD, depression, and bipolar disorders, all of which display impaired social interaction, we examined whether a deficiency of GPR50 is linked to defective social behaviors by subjecting the mice to a three-chamber test." (PMID 39143050, 2024). "Thus, the exact role of GPR50 remains unclear and further investigation in other populations, including the elderly, is warranted, especially given the relatively high heritability of depression but lack of clearly identified genetic risk factors to date." (PMID 25798330, 2015). "Together this suggests that GPR50 does not appear to be a good candidate gene for depression." (PMID 25798330, 2015).
bipolar disorder (6 papers, 2010 to 2024). A disorder of the brain that causes unusual shifts in mood, energy, activity levels and the ability to carry out day-to-day tasks. "Since GPR50 influences neurite outgrowth and the Δ502–505 variant was previously associated with bipolar disorder in females, a possible association of this gene with ASD warrants further genetic and functional studies." (PMID 20657642, 2010).
Obesity (5 papers, 2011 to 2025). Accumulation of substantial excess body fat. "From this study, it appears that GPR50 has an inhibitory effect on inflammation in adipocyte 3T3‐L1 cells, and that chronic tissue inflammation is an important cause of IR induced by obesity." (PMID 36333974, 2023). "On the other hand, GPR50 has been shown to play a role in the regulation of energy metabolism and obesity." (PMID 40243421, 2025). "GPR50 knockout mice have higher metabolic rates and less fat accumulation and are partially resistant to diet‐induced obesity." (PMID 36333974, 2023). "We have previously reported that Gpr50−/− mice exhibit reduced weight gain, elevated metabolic rate and partial resistance to diet-induced obesity." (PMID 21858214, 2011). "Specifically, Gpr50 expression in the brain is highly responsive to energy status being decreased by both fasting and high fat diet feeding, and Gpr50−/− mice demonstrate elevated metabolic rate, reduced fat accumulation, and partial resistance to diet-induced obesity." (PMID 21858214, 2011). "This orphan G protein‐coupled receptor is implicated in regulation of energy expenditure; mice lacking Gpr50 weigh less and are protected from diet induced obesity, likely due to increased energy expenditure." (PMID 37713040, 2023).
mood disorder (4 papers, 2015 to 2025). A cognitive disorder a disturbance in which the person's mood is hypothesized to be the main underlying feature. "The sex-specific association between the variant of GPR50 and mood disorders in females suggest that GPR50 may be a female-specific risk for mood disorder." (PMID 27992373, 2017). "Across both regions, G‐protein coupled receptor 50, involved in thermoregulation, sleep, and sex‐related mood disorders, was significantly altered, but in opposite directions." (PMID 40659452, 2025).
breast carcinoma (3 papers, 2018 to 2023). "In vivo GPR50 protects against tumor development in mice and low GPR50 levels associate with poor survival prognosis in human breast cancer." (PMID 29572483, 2018). "Low GPR50 levels are associated with poor survival prognosis in human breast cancer (independently of the breast cancer subtype)." (PMID 29572483, 2018). "Kaplan–Meier analysis confirmed that low GPR50 expression is associated with poor relapse-free survival prognosis in 3951 breast cancer patients." (PMID 29572483, 2018). "As GPR50 expression in CSLC is significantly higher than that in other breast cancer cells, we first investigated the properties of CSLC that can be regulated by GPR50 expression." (PMID 36769125, 2023). "Recent studies also reported that GPR50 can act as a tumor suppressor in breast cancer (BRC);27,28 however, there is limited research on the role of GPR50 in cancer progression." (PMID 32405532, 2020). "This indicates that GPR50 affects cell proliferation in breast cancer and lung carcinoma-derived cells." (PMID 29572483, 2018). "Taken together, low GPR50 expression appears to be an independent marker of poor survival prognosis in breast cancer." (PMID 29572483, 2018). "To study the relevance of the GPR50/TβRI complex on cell proliferation and tumor development we choose the MDA-MB-231 breast cancer cell line in which we were able to recapitulate the spontaneous Smad2 and Smad3 phosphorylation in the presence of GPR50." (PMID 29572483, 2018). "GPR50 exhibits TGFβ-like properties, a new tumor suppressor limiting spontaneous mammary tumor development in the MMTV/Neu mouse model and GPR50 underexpression is associated with cancer development and poor survival prognosis." (PMID 29572483, 2018). "Inversely, targeted deletion of GPR50 in the MMTV/Neu spontaneous mammary cancer model shows decreased survival after tumor onset and increased tumor growth." (PMID 29572483, 2018). "The G protein-coupled receptor 50 (GPR50) gene is a member of the GPCRs implicated in antiproliferative effects, and poor survival prognosis is related to the low expression of GPR50 in breast cancer." (PMID 36769125, 2023). "GPR50 protein might be involved in the regulation of breast cancer, which might be involved in sphere formation, migration, and stemness of breast cancer stem-like cells." (PMID 36769125, 2023). "In addition, the survival rate graph of breast cancer patients with high GPR50 levels on the R2 gene analysis platform showed a lower survival rate." (PMID 36769125, 2023). "However, little is known regarding the role of GPR50 in the regulation of breast cancer stem-like cells." (PMID 36769125, 2023). "In this study, we investigated whether GPR50 knockdown decreased proliferation, migration, and sphere formation in breast cancer stem-like cells." (PMID 36769125, 2023). "This study found that GPR50 expression was higher than that of other genes in CSLC-converted BC cell lines obtained from chemotherapy-treated patients, suggesting that GPR50 may be involved in breast cancer stem cell regulation." (PMID 36769125, 2023). "As GPR50 was described as a tumor suppressor in breast cancer, we examined whether GPR50 plays an oncogenic or a tumor-suppressor role in HCC." (PMID 32405532, 2020). "Low GPR50 expression is associated with poor survival prognosis in human breast cancer irrespective of the breast cancer subtype." (PMID 29572483, 2018). "Interestingly, the survival of the patients decreased with low expression of GPR50 even after accounting for the four molecular breast cancer subtypes: luminal A, luminal B, Her-2, and basal-like." (PMID 29572483, 2018). "Additionally, the expression level of GPR50 regulates clinical prognosis of breast cancer." (PMID 36769125, 2023). "The expression of GPR50 in CSLC and several breast cancer cell lines was assessed by RT-PCR and online platform (UALCAN, GEPIA, and R2 gene analysis)." (PMID 36769125, 2023).
breast carcinoma (continued). "Additionally, it was discovered that breast cancer patients with poor DMFS and OS had increased GPR50 expression." (PMID 36769125, 2023). "Here the authors show that the orphan G-protein coupled receptor GPR50 can activate the TGFβ receptor I, in the absence of TGFβ, by stabilizing its active conformation and show antitumor activity in a mouse model of breast cancer." (PMID 29572483, 2018). "Inversely, silencing of endogenous GPR50 in NCI-H520 cells promotes cell proliferation and GPR50ko mice show decreased survival after tumor onset and increased tumor growth in the MMTV/Neu spontaneous mammary cancer model." (PMID 29572483, 2018).
hepatocellular carcinoma (3 papers, 2020 to 2024). A malignant tumor that arises from hepatocytes. "In addition, previous studies have revealed that GPR50 is a key gene that can treat cancer through Notch signaling in various hepatoma cells." (PMID 36769125, 2023). "A previous study reported that several GPCRs, including GPR50, are involved in the reprogramming of somatic cells to BCSCs, suggesting that GPR50 can act as a tumor suppressor in hepatocellular carcinoma (HCC) through the ADAM17-Notch signaling pathway." (PMID 36769125, 2023). "GPR50, significantly upregulated in hepatocellular carcinoma (HCC) patients and the CBRH-7919 cell line, promotes HCC progression by enhancing cell proliferation, migration, and autophagy, mediated through interactions with CCT6A and PGK1, suggesting GPR50 as a potential therapeutic target for HCC." (PMID 39315094, 2024).
lung carcinoma (3 papers, 2018 to 2022). "Interestingly, GPR50 is down-regulated in breast, cervical, ovarian and lung cancers while up-regulated in liver cancer." (PMID 35694242, 2022). "The GEO data showed that GPR50 expression was significantly upregulated in liver cancers (i.e., HCC) and downregulated in breast, cervical, esophagus, and lung cancers, which is in contrast with the expression patterns in the Oncomine database." (PMID 32405532, 2020).
Anxiety (2 papers, 2015 to 2017). Intense feelings of nervousness, tension, or panic often arise in response to interpersonal stresses. "None of the prior studies investigating GPR50 have considered antidepressant treatment or anxiety comorbidity either, which is frequent in the elderly and may reflect greater severity of the disorder." (PMID 25798330, 2015).
liver cancer (2 papers, 2020 to 2022). An epithelial or non-epithelial malignant neoplasm that arises from the liver. "We then examined mutation and copy number alterations (CNAs) in the liver cancer TCGA dataset through the cBioPortal web and found that approximately 3% of the samples showed mutation, amplification, deep deletion, or mRNA upregulation of GPR50 genes." (PMID 32405532, 2020). "We further examined GPR50 expression in liver cancer using TCGA dataset through the SurvExpress web and confirmed GPR50 overexpression." (PMID 32405532, 2020). "However, little is known regarding the biological significance of GPR50 in liver cancer." (PMID 32405532, 2020).
mental disorder (2 papers, 2015 to 2024). A disease that has its basis in the disruption of mental process. "Candidate gene studies have also reported associations between variants in the GPR50 gene and psychiatric disorders in women." (PMID 25798330, 2015). "G-protein-coupled receptor 50 (GPR50) has been implicated in psychiatric disorders in a small number of studies, although not consistently." (PMID 25798330, 2015).
Insulin resistance (1 paper, 2023). Increased resistance towards insulin, that is, diminished effectiveness of insulin in reducing blood glucose levels. "The aim of this study was to investigate the effect of GPR50 on inflammation and insulin resistance in 3T3‐L1 preadipocytes." (PMID 36333974, 2023).
triple-negative breast carcinoma (1 paper, 2023). An invasive breast carcinoma which is negative for expression of estrogen receptor (ER), progesterone receptor (PR), and human epidermal growth factor receptor 2 (HER2). "Next, the UALCAN dataset confirmed the high expression of GPR50 in the tissues of triple-negative breast cancer (TNBC) patients." (PMID 36769125, 2023).